CRP (C-reactive protein)
Diseases named in the same sentence as CRP in open-access papers (continued):
Sharing a sentence is not in itself a finding about the gene and the disease.
coronary artery disease (continued). "Most notably, elevated CRP and IL6 levels have been found to be associated with increased risk of coronary heart disease events in many large prospective observational studies." (PMID 34168680, 2021). "Regarding the risks of cardiovascular disease, especially coronary heart disease, CRP levels >3 μg/ml before periodontal treatment are suggestive of a high risk of coronary heart disease." (PMID 33603787, 2021). "C-reactive protein (CRP) is a well-studied inflammation-related molecule associated with many chronic inflammatory diseases, such as acute and chronic heart failure, coronary heart disease, and inflammatory bowel disease." (PMID 34465395, 2021). "Similar effect was observed in patients with coronary artery disease after 6–8 weeks of moderate intensity aerobic exercise training: salivary high-sensitivity CRP level decreased after 24 sessions of CR but these are examples of distant effects." (PMID 33616017, 2021). "In a later study, increased waist circumference and augmented serum leptin levels occurred concomitant to elevated serum cholesterol, triglyceride and CRP expression in coronary artery disease (CAD) patients compared with healthy controls." (PMID 34064112, 2021). "The inverse association demonstrated between VO2peak and levels of sCD14 and CRP, suggests a significant interaction between cardiorespiratory fitness and gut-related inflammation in our patients with both type 2 diabetes and coronary artery disease." (PMID 33794977, 2021). "Nevertheless, C3G-rich black rice has demonstrated therapeutic benefits by reducing C reactive protein (CRP) in coronary heart disease patients when consumed long term." (PMID 34359469, 2021). "By contrast, we did not identify a significant causal effect of childhood maltreatment on autism, bipolar disorder, coronary artery disease, type 2 diabetes, C-reactive protein concentration, or vice versa (appendix pp 45–60, 93)." (PMID 33740410, 2021). "The black rice pigment fraction significantly decreased plasma levels of soluble vascular cell adhesion molecule-1 (sVCAM-1), soluble CD40 ligand (sCD40L), and high sensitivity C-reactive protein (hs-CRP) in patients with coronary heart disease." (PMID 34917106, 2021). "In conclusion, we provide evidence for genetic correlations between BMI, CRP, T2D and coronary artery disease with FEV1, FVC and their ratio." (PMID 34154662, 2021). "When stratifying patients according to mortality, variables independently associated with mortality were age, other cardiovascular diseases except for coronary artery disease, C-reactive protein, lactate dehydrogenase levels, and IMV." (PMID 37386623, 2021). "The hs-CRP cutoff value in predicting coronary artery disease in Japanese individuals is 1.0 mg/L37." (PMID 34262126, 2021). "C-reactive protein (CRP) is the main chronic inflammation biomarker, it has been associated with an increase in risk for coronary heart disease and cardiovascular disease mortality." (PMID 34572597, 2021). "The next example we investigated was C-reactive protein which is known to be involved in coronary heart disease." (PMID 32019214, 2020). "Accordingly, the inhibitory effect of CRP on the ATP-induced interleukin-1β release was blunted in monocytes from coronary heart disease patients treated with atorvastatin compared to monocytes obtained before medication." (PMID 33080990, 2020). "The present study also found that C-reactive protein and history of coronary artery disease were significantly higher in stable and unstable angina patients than controls." (PMID 32351734, 2020). "C-reactive protein and interleukin-6 are inflammatory derivatives produced in the presence of periodontitis and in the pathophysiology of coronary disease." (PMID 32215496, 2020). "CRP was analyzed for its relation to atherosclerosis, coronary artery disease (CAD), acute coronary syndromes, and heart failure (HF), and it is now considered to play a role in growth and development of HF." (PMID 32676505, 2020).
coronary artery disease (continued). "It was suggested that increased CRP levels were found in cardiovascular diseases such as coronary heart disease." (PMID 32019214, 2020). "It modulates immune responses: exercise decreases C-reactive protein (CRP) and IL-6 levels in type II diabetes, and reduces CRP and fibrinogen levels in patients with coronary artery disease." (PMID 32751902, 2020). "Serum CP-IgA, hs-CRP and IL-6 levels increased with the severity of the coronary artery disease (P < 0.05), and the serum hs-CRP and IL-6 levels of patients with perioperative cardiovascular events were higher (P < 0.05)." (PMID 31088358, 2019). "Serum CRP-to-albumin ratio has been shown previously to be a predictor for overall survival in several cancer states and in coronary artery disease." (PMID 31828049, 2019). "This study concluded that high concentration CRP increases the odds of coronary artery disease (OR = 1.45; 95% CI: 1.25–1.68) and that garlic consumption can improve cardiovascular health via lowering pro-inflammatory cytokines." (PMID 30683061, 2019). "Serum CRP level increases during acute myocardial infarction and is considered a valuable prognostic marker of ischemic heart disease." (PMID 31063484, 2019). "There is evidence that patients with rhino-sinusitis and CB have higher levels of C-reactive protein, a predictive marker of coronary heart disease." (PMID 31697758, 2019). "Another group reported a significant correlation between CRP and the Framingham Coronary Heart Disease Risk Score (FCRS), although the correlation between CRP and most individual components of the FCRS was minimal." (PMID 30934586, 2019). "The differences in serum CP-IgA, hs-CRP and IL-6 levels between patients with different severities of coronary artery disease and subjects in the control group were statistically significant (P = 0.000)." (PMID 31088358, 2019). "Of note, 79% have available data on plasma CRP (C-reactive protein), while coronary disease burden information, from invasive angiography is available in 52% of studies." (PMID 30896328, 2019). "In patients with infarction, this is due to presence of coronary artery disease, but also due to a lower mean ejection fraction and higher serum CRP." (PMID 30266917, 2018). "Elevated CRP levels also correlate with worse cardiac function, and worse functional capacity in patients with ischemic heart disease and systolic HF." (PMID 30619885, 2018). "Several studies concluded that CRP level predicts ischemic heart disease, cerebrovascular disease, and cardiovascular death even after adjustment for the traditional Framingham covariates." (PMID 30169521, 2018). "For example, 14,15-DHET levels correlate with high sensitivity C-reactive protein levels and are significantly higher in people with coronary heart disease." (PMID 29986999, 2018). "Multivariate logistic regression analysis identified five independent mortality predictors: severe coma, elevated CRP, cancer, coronary artery disease, and bandemia." (PMID 29915256, 2018). "Emerging evidence suggests that elevated circulating CRP concentration has become an independent predictor of coronary heart disease." (PMID 29330688, 2018). "Five independent mortality predictors were identified: severe coma (Glasgow Coma Scale score ≤8), past histories of cancer and coronary artery disease, elevated C-reactive protein levels (>10 mg/dl), and bandemia (>10% band cells)." (PMID 29915256, 2018). "The CRP pattern unlikely mirrors the curves for coronary heart diseases, where significant reductions are already evident after 2 to 3 years since smoking cessation." (PMID 30150729, 2018). "The aim of this study was to investigate the predictive value of single and repeated measurements of GDF-15 compared to Cystatin C and CRP for incidence of heart failure (HF) and death due to coronary heart disease (CHD) in the general population." (PMID 29771963, 2018).
coronary artery disease (continued). "CRP was used as a target analyte, since CRP is a useful biomarker for coronary artery disease and inflammation." (PMID 29278402, 2017). "A recent study showed that a high PLR is related to the presence of coronary artery disease and is correlated with C-reactive protein and fibrinogen levels." (PMID 28882170, 2017). "C-reactive protein was measured in serum samples at baseline from 2420 men aged 42–61 years, from the Kuopio Ischemic Heart Disease study." (PMID 28718029, 2017). "Moreover, CRP has been used to forecast the risk of coronary heart disease, suggesting that there may be a positive link between abnormal blood sugar levels and coronary heart disease." (PMID 28716139, 2017). "In coronary artery disease CRP concentrations found in the general population (1–3 μg/ml) predict increased cardiovascular mortality." (PMID 27352030, 2016). "C-reactive protein (CRP) is a commonly used inflammatory marker and elevated CRP levels are shown to increase the risk of coronary artery disease (CAD)." (PMID 26266345, 2015). "One of the acute phase proteins HNF-1α regulates is C-reactive protein (CRP), which is used to monitor inflammation and possible progression of coronary heart disease." (PMID 26413797, 2015). "CAC also performs better compared with carotid intima-media thickness and highly sensitive C-reactive protein in prediction of coronary heart disease and cardiovascular disease events." (PMID 25807266, 2015). "For instance, human population studies have associated interleukin-6, C-reactive protein and TNF-α to age-related chronic diseases, like coronary heart disease and disability." (PMID 25888078, 2015). "For example, in patients with stable coronary artery disease, circulating C-reactive protein, and IL-6 levels were significantly reduced after regular EXE by 41 and 18%, respectively." (PMID 26600018, 2015). "The level of C-reactive protein (CRP) in the peripheral blood is used as a biomarker of systemic inflammation, and is associated with increased risk of coronary heart disease, vascular death, and cancer death." (PMID 26218286, 2015). "One of the inflammatory markers proven to be of predictive value to both ACS development and established coronary artery disease is the short Pentraxin C-reactive protein (CRP)." (PMID 24737925, 2014). "In patients at risk of coronary disease, however, rosuvastatin is highly effective not only when it comes to reducing LDL cholesterol; it also effectively reduces CRP, as well as the number of cardiovascular events and death." (PMID 24586994, 2014). "CRP is a moderate predictor of coronary heart disease and, apart from periods of acute illness, its concentration remains relatively stable over time." (PMID 25237581, 2014). "Further studies are needed however to investigate the correlation between levels of CRP produced by arterial macrophages, and the prediction of coronary artery disease." (PMID 24588988, 2014). "APOE variants have been associated with blood lipid levels, familial dyslipoproteinemia, polygenic dyslipidemia, elevated plasma C-reactive protein levels, coronary heart disease, and myocardial infarction." (PMID 24922540, 2014). "Myeloperoxidase is a hemoprotein that abundant in rupture plaques and useful as a clinical tool in coronary artery disease (CAD), however it is inferior to CRP as a marker for risk stratification." (PMID 25237354, 2014). "Statin-related lowering of C-reactive protein levels was recently shown to improve coronary artery disease outcomes in a randomized controlled trial." (PMID 24465425, 2014). "Several studies have shown that CRP is inversely associated with EPA and DHA levels in both healthy subjects and in patients with stable coronary artery disease." (PMID 24578648, 2014). "They had a significantly higher body mass index, systolic and diastolic blood pressure, C-reactive protein level, history of coronary heart disease and prevalence of antihypertensive medications use." (PMID 24265674, 2013).
coronary artery disease (continued). "The levels of HMGB1 were positively correlated with hs-CRP and cardiac troponin I levels (r=0.657 and 0.554, respectively; both P<0.01) in patients with coronary artery disease." (PMID 23935732, 2013). "A previous study has shown that hs-CRP is correlated with the process and prognosis of coronary artery disease and is an independent predictor of coronary events." (PMID 23935732, 2013). "The levels of serum HMGB1, hs-CRP and cardiac troponin I were measured in 98 patients with coronary artery disease and in 30 healthy subjects." (PMID 23935732, 2013). "The present study examined the association of MS score with high sensitivity C-reactive protein (hs-CRP), interleukin-6 (IL-6), resistin, adiponectin, and angiographic coronary artery disease (CAD) severity according to the presence of DM." (PMID 24088407, 2013). "Both IL-6 and CRP are widely used markers for systemic inflammation and predictors of coronary heart disease." (PMID 24229441, 2013). "Patients with coronary artery disease submitted to adequate chronic training with increase in the VO2max have lower levels of CRP compared with basal values." (PMID 22566996, 2012). "Mixed effects models were performed for CRP, IL-6, and IP-10, adjusting for the following covariates: access type, coronary artery disease, sex, age, race, HD initiation, diabetes mellitus, infection, access thrombosis, and number of days after access surgery." (PMID 22121485, 2012). "Weak but significant positive correlation with CRP, as found in our study, has also been identified in patients with coronary disease." (PMID 22574168, 2012). "In addition, valsartan therapy for 8 months reduced CRP by 39% in hypertensive patients with left ventricular hypertrophy or with other cardiovascular risk factors, while 3 months of irbesartan therapy for patients with coronary artery disease significantly reduced the plasma CRP level." (PMID 22583484, 2012). "C-reactive protein (CRP) is a biomarker for inflammation and is associated with increased coronary artery disease and cardiovascular events." (PMID 22645408, 2012). "In stable and unstable coronary artery disease, elevated CRP reflects inflammation in the vascular bed or vulnerability of unstable plaques in contrast to MI, where the inflammatory response to myocardial necrosis dominates." (PMID 22446726, 2012). "Used as a marker of systemic inflammation, elevated serum levels of CRP have been associated with a wide range of detrimental outcomes, and are often clinically used to guide risk factors modification of stable coronary artery disease (CAD)." (PMID 22708908, 2012). "A previous study showed significant decreased levels of CRP in dyslipidemic patients with coronary artery disease treated with simvastatin 20 mg per day for 4 months." (PMID 21214952, 2011). "The prognosis of coronary heart disease is negatively influenced by the levels of cotinine due to SHS exposure, evolving together with the levels of fibrinogen, homocystein and CRP (all correlated with the coronary risk)." (PMID 21556172, 2011). "Recently, HNF1α single nucleotide polymorphisms (SNPs) have been associated with plasma C-reactive protein (CRP), LDL cholesterol and gamma glutamyltransferase (GGT), and coronary heart disease." (PMID 21203500, 2010). "Two studies reported the time elapsed between first lifetime presentation with coronary disease and assessment of CRP." (PMID 20532236, 2010). "In another study, the incidence of coronary heart disease was highest in the patients with both elevated CRP and D-dimer." (PMID 20140090, 2010). "We investigated the association of the rs2259816 polymorphism in the HNF1A gene with the circulating level of C-reactive protein and the hazard of coronary artery disease in the LURIC Study cohort." (PMID 21062467, 2010).
coronary artery disease (continued). "When taken individually, Hs-CRP was positively correlated to severity of coronary diseases in the middle age group (group II, P < 0.03) and the old age group (group III, P < 0.01) but not in the young group <45 years." (PMID 20508763, 2009). "During destabilization of coronary heart disease, cytokines released by inflammatory cells mediate further inflammatory cell migration and cardiac repair and, particularly IL-6, mediates CRP elevation." (PMID 19503842, 2009). "As regard the severity of coronary diseases, Hs-CRP was positively correlated with coronary severity score (r = 0.249, P < 0.002) and the number of vessels diseased (r = 0.314, P < 0.001) just in whole ACS patients." (PMID 20508763, 2009). "Taken together, the systolic blood pressure and C reactive protein were higher in the patient with ischemic heart disease (both CABG and angina pectoris)." (PMID 19706169, 2009). "In agreement, the patients with ischemic heart disease had higher plasma levels of C reactive protein." (PMID 19706169, 2009). "The role of CRP as a marker during and after ischemic stroke is less extensively studied in comparison to coronary artery disease." (PMID 19400931, 2009). "In the present study, the observed plasma levels of C reactive protein was elevated in patients with ischemic heart disease." (PMID 19706169, 2009). "Previously, an inverse correlation between expression levels of CRP and adiponectin in adipose tissue from the patients with coronary artery disease had been demonstrated." (PMID 17903275, 2007). "Elevated CRP concentrations has been shown to be associated with increased risk for CHD, ischemic stroke, peripheral arterial disease, and ischemic heart disease mortality in healthy men and women." (PMID 18078524, 2007). "CETP TaqIB polymorphism is significantly associated with the presence of AF in the context of micro- or macroalbuminuria, elevated C-reactive protein, renal dysfunction, and ischemic heart disease." (PMID 16623947, 2006). "Other significant models were the combination of CRP >3 mg/L and the CETP TaqIB polymorphism, the combination of renal dysfunction and the CETP TaqIB polymorphism, and the combination of ischemic heart disease and CETP TaqIB polymorphism (P < 0.05)." (PMID 16623947, 2006). "C-reactive protein (CRP) is the marker of inflammation most widely studied in patients with coronary artery disease and hence has become the marker of reference for any other inflammatory-based disease." (PMID 16774687, 2006). "The Fragmin during Instability in Coronary Artery Disease (FRISC) trial study showed that elevated CRP levels at admission in ACS patients could predict increased long-term mortality." (PMID 41607462, 2026). "It has been shown that CRP correlates with the severity of coronary heart disease." (PMID 39691830, 2025). "The preliminary observation that helped the development of trials with colchicine was the finding of decreased high-sensitivity levels of C-reactive protein after 30 days of treatment with colchicine in patients with stable coronary disease on optimal medical therapy." (PMID 39661542, 2025). "Additionally, a combination of serum albumin and CRP has been studied in patients with coronary artery disease who have undergone PCI, where a findings showed that higher CAR was found to be associated with an increased risk of mortality." (PMID 40636825, 2025). "Among the 7 features, APTT, RDW, CRP exhibited strong correlation with coronary artery disease." (PMID 40893933, 2025). "C-reactive protein remains one of the most studied acute-phase proteins in ischemic heart disease." (PMID 41226718, 2025). "Recent clinical trials demonstrated that proprotein convertase subtilisin/kexin 9 (PCSK9) inhibitors reduce cardiovascular events without affecting systemic inflammation in the patients with coronary artery disease, as determined by high sensitivity C-reactive protein (CRP) levels." (PMID 39149582, 2024).